CLDN1 (claudin 1)
Diseases named in the same sentence as CLDN1 in open-access papers (continued):
Sharing a sentence is not in itself a finding about the gene and the disease.
vitamin A deficiency (1 paper, 2023). Deficiency of vitamin A due to malnutrition, malabsorption, or dietary lack. "Vitamin A deficiency caused a colon-intestinal barrier in mice, which not only reduced the secretion of immunoglobulin A, but also down-regulated the colon-tight-junction-related protein Occludin and Claudin-1." (PMID 38136169, 2023).
Zinc deficiency (1 paper, 2020). A deficiency of the essential metal Zinc; an essential cofactor for many enzymes. "In this study, zinc deficiency caused by treatment with both TPEN and HMGB1 disrupted the epithelial barrier and induced permeability via downregulation of TJ molecules LSR, TRIC, CLDN-1 and pMAPK in Caco-2 cells in 2.5D cultures." (PMID 33182652, 2020).
tumor (218 papers, 2005 to 2026). "Other key PGR-regulated genes were associated with the invasion of cells such as Cxcr4 and Cldn1, two membrane-localized proteins involved in tumor cell invasion and migration." (PMID 35563869, 2022). "We further investigated the relationships between PD-L1 and Claudin-1, which were highly expressed and associated with tumor aggressiveness in FTC." (PMID 35818041, 2022). "Our in vivo study demonstrated that CLDN1 expression is associated with greater tumor burden and resistance to treatment, though this result was not statistically significant." (PMID 33828978, 2021). "E-cadherin, nuclear β-catenin and claudin-1 are also associated with other important prognostic factors, including nodal metastasis, tumor deposits, and elevated serum CA 19–9 levels." (PMID 34214117, 2021). "Immunohistochemical analysis revealed that the presence of CLDN-1 in the invasive front of tumor islands was associated with neck mode metastasis." (PMID 31952355, 2020). "Some studies have shown that the decreased expression of claudin-1 indicates worse prognostic and aggressive tumor behaviors and linked with higher histological grade, invasion depth, and lymph invasion in CRC." (PMID 32855635, 2020). "This study showed a positive association of CLDN-1 expression with the degree of tumor differentiation and lymph node metastasis." (PMID 31952355, 2020). "The expression level of CLDN1 was found to be associated with tumor differentiation and age in several kinds of cancers." (PMID 30910845, 2019). "CLDN1, which encodes Claudin-1, is expressed in a tissue-specific manner and is involved in the proliferation, invasive ability, and metastasis of tumor cells." (PMID 28126724, 2017). "Claudin-2 upregulation accompanied by claudin-1 downregulation was associated with tumor progression." (PMID 27547510, 2016). "Downregulation of claudin-1 and claudin-5 has been detected in human glioma and has been associated with tumor progression." (PMID 27547510, 2016). "The resultant positive staining for CLDN-1, -2, and -3 that was associated with decreased expression of Slug and fascin differentiated the orthotopic tumor tissues with miR-30a overexpression from those carrying vector alone." (PMID 26918943, 2016). "Similar to Nm23H1, CLDN1 was predominantly expressed close to the basal layer of the non-tumor mucosal epithelium with membrane-associated localization." (PMID 27376780, 2016). "In our previous study, we found that CLDN1 gene expression was highly associated with reduced post-operative survival, and that IL-8 was the most highly upregulated gene in the tumor specimens." (PMID 26984265, 2016). "Claudin1 (CLDN1) is a member of the tetraspan transmembrane protein family that plays a major role in tight junctions and is associated with tumor metastasis." (PMID 26067567, 2015). "Taken together, these results suggested that increased claudin-1 expression enhances susceptibility to tumor development in the colon of APCMin mice as well as contributes to the tumor progression." (PMID 24997475, 2014). "Based on tumor biology, down-regulation of CLDN1 would result in destruction of tight junctions and loss of cell-to-cell adhesion causing tumor progression, however the clinical significance in gastric carcinogenesis is more complex." (PMID 24321518, 2013). "The expression of claudin-1 is elevated in many types of cancer cells and is proposed to be potentially causally involved in tumor growth and progression." (PMID 23685873, 2013). "Indeed, 10 tumor specimens were found to be strongly positive for CLDN1 expression among 12 high-risk GIST samples being analyzed." (PMID 40943068, 2025). "Reduced expression of CLDN1 is closely associated with tumor metastasis." (PMID 41249135, 2025).
tumor (continued). "The correlation between high Cldn1 expression and poor overall survival further underscores its potential role as a prognostic marker in PDAC, which is consistent with studies in other cancer types where Cldn1 has been associated with tumor aggressiveness and metastasis." (PMID 40361399, 2025). "Indeed, we found that CLDN1 expression increased in most of the tumor specimens from intermediate- to high-risk GIST." (PMID 40943068, 2025). "The down-regulation of tight junction proteins claudin-1, occludin, and ZO-1 may be associated with tumor proliferation, invasion, and metastasis." (PMID 39465423, 2024). "Overall, CLDN1 has been associated with diseases such as tumour development and epithelial dysfunction; we speculate that CLDN1 is linked to the prognosis of various other diseases." (PMID 39457456, 2024). "On the contrary, levels of Cldn1,Cldn4,Cldn6,Cldn9,Cgn,F11r, and Cdh1, associated with exacerbated inflammation, perturbation of the TJ assembly, and even with mesenchymal transformation or tumour progression, were overexpressed." (PMID 37794493, 2023). "As the histological tumor regression is associated with the clinical outcome, high post-chemotherapy CLDN1 expression might indicate poor prognosis." (PMID 37041570, 2023). "Furthermore, it has been indicated that reduced CLDN1 expression is an independent predictor of tumour recurrence associated with poor patient outcomes." (PMID 38201579, 2023). "For example, high expression of claudin-1 (CLDN1) is associated with high-risk tumor behavior." (PMID 34571860, 2021). "Similarly, in a previous study, the overexpression of CLDN-1 was reported in association with a larger tumor size." (PMID 33407452, 2021). "In summary, decreased expression of the epithelial markers E-cadherin, claudin-1, and β-catenin nuclear location are statistically associated with other important prognostic factors, including nodal metastasis, tumor deposits, and elevated serum CA 19–9 levels." (PMID 34214117, 2021). "CD9 prevents the association between CLDN-1 and tight junctions that could cause the progression of the tumor." (PMID 31952355, 2020). "Decreasing claudin-1 has been related to TJ dysfunction, with subsequent dissociation and loss of cell polarity, which may be involved in tumor progression, invasion and metastasis." (PMID 32518268, 2020). "Claudins in intestinal cytomembrane maintain the intestine's homeostasis; thus, abnormal expression of claudins may result in various pathophysiological conditions, and the loss of claudin-1 expression leads to tumor invasion and metastasis." (PMID 32855635, 2020). "If indeed CD9 prevents claudin 1 from associating with the TJ, then this could promote tumor progression." (PMID 26633531, 2015). "Both downregulation and overexpression of claudin 1 have been associated with tumorigenesis, suggesting that claudin 1 may alternatively function as a tumor suppressor or as an oncogene." (PMID 23844228, 2013). "In addition, meta-analysis showed that claudin-1 was associated with early tumor stage (n = 3; RR, 0.75; 95% CI, 0.54–1.04; P = 0.09) and negative lymph node metastasis(n = 4; RR, 0.91; 95% CI, 0.82–1.02; P = 0.10), although it was not statistically significant." (PMID 32855635, 2020). "Moreover, although both Nm23H1 and CLDN1 have been linked to tumor progression in the literature, whether there is any interaction between them has not been reported previously." (PMID 27376780, 2016). "Claudin-1 primarily acts as a tumor promoter by enhancing the invasive and motility capabilities of cancer cells." (PMID 41399659, 2026). "Investigation highlights CLDN1 as one of the most deregulated claudins in human cancers, acting as either a tumor promoter or suppressor depending on the specific cancer type." (PMID 41399659, 2026). "Mechanistically, PABPC3 promotes tumor metastasis by modulating the expression of CLDN1, a critical component of tight junctions." (PMID 41249135, 2025).
tumor (continued). "Mechanistically, CLDN1 promotes tumor progression by regulating apoptosis resistance, particularly through β-catenin-mediated pathways." (PMID 40687428, 2025). "Reduced CLDN1 and altered localization (cytoplasmic relegalization or loss from junctions) have been associated with EMT and tumor progression." (PMID 40687428, 2025). "In this pathway, downstream mediators including iPLA2, PGE2, 15-keto PGE2, and PPARγ have all been shown to enhance CLDN1 transcription in A549 cells, highlighting the tight junction protein’s involvement in inflammation-driven tumor progression." (PMID 40687428, 2025). "CCFM683 inhibited the NF-κB signaling pathway, up-regulated MUC2, Claudin-1, and ZO-1, and promoted tumor cell apoptosis via the CLA-PPAR-γ axis." (PMID 39924893, 2025). "Consistent with the tumor metastatic analysis, high expression of CLDN1 (hazard ratio (HR) > 1.3; p < 0.01) and INHBA (HR > 1.5; p < 0.001) was associated with poor prognosis, as indicated by a high HR." (PMID 40426863, 2025). "This seems counterintuitive given CLDN1’s pro-tumor role described elsewhere; it suggests a subset of CRCs undergo claudin switching where CLDN1 is lost in very advanced tumors, possibly due to EMT." (PMID 40687428, 2025). "In our study, CLDN1 expression was significantly up-regulated in a tumor progression-dependent manner." (PMID 40426863, 2025). "Significantly upregulated eRNAs were identified near key oncogenes, including CLDN1, TP63, and EGFR, confirming transcriptional activation at these tumor-associated SEs." (PMID 41323280, 2025). "CLDN1 is correlated with tumor infiltration, metastasis, enhanced anoikis resistance, poor survival, cell aggregation, cell migration, and colonization." (PMID 41440381, 2025). "Specifically, claudins such as claudin-1, -2, -3, -4, and -7 exhibit diverse expression patterns that correlate with tumor aggressiveness, patient survival rates, and response to therapies." (PMID 39364319, 2024). "Compared with normal group, the expression of occluding, claudin-1, ZO-1 and Muc2 in tumor model group were prominently reduced, but they were all restored after the intervention of XRZYBXD." (PMID 40046008, 2024). "The overexpression of CLDN1 in both mouse and in vitro studies demonstrated increased tumor growth, development of metastases, and resistance to apoptosis." (PMID 38540693, 2024). "According to this theory, peripheral Cldn1 perpetuates tumorigenesis by activating the recruitment of tumor-infiltrating M2 macrophages, which is consistent with the reported role of Cldn1 in pro-HCC." (PMID 39548562, 2024). "TMX4, ALPL, PTX3, BHLHE40, TNFRSF12A and CST3 demonstrated significant overexpression in LUSC tumour tissues, whereas CLDN1, VKORC1 and ADD3 exhibited significant underexpression in the HPA database." (PMID 38520221, 2024). "In our study, compared with normal group, the expression of occluding, claudin-1 and ZO-1 in tumor model group were prominently reduced, but they were all restored after the intervention of XRZYBXD." (PMID 40046008, 2024). "A humanized-mouse IgG1 antibody targeting CLDN1 (xi-342) was found to significantly accumulate within HT-1080 xenograft tumors when compared to control IgG1 antibodies, which attenuated tumor growth through ADCC." (PMID 38371623, 2024). "The oxaliplatin dose was halved when combined with the ADC targeting CLDN1 (6F6-MMAE) and caused a significant reduction in tumor growth and prolonged survival when compared to oxaliplatin alone." (PMID 38371623, 2024). "Loss of claudin-1 has been shown to have a dual effect in promoting and suppressing tumor progression across cancers, and depletion of claudin-1 increases PDAC tumor growth and metastasis." (PMID 37046830, 2023). "Immunohistochemical (IHC) staining was performed on formalin fixed paraffin embedded (FFPE) tumor tissues, and CLDN1, -2, -3, -4, -5, -7, and -18 protein expressions were analyzed." (PMID 37621953, 2023).
tumor (continued). "Claudin proteins are extensively studied, and various claudin proteins, including claudin-1, claudin-4, and claudin-18.2 have high specificity and sensitivity in tumor diagnosis." (PMID 36959784, 2023). "In bladder carcinoma cell lines, ΔNp63 promotes tumor invasion and metastasis through overexpression of claudin-1, and knockdown of the isotype blunts these effects." (PMID 38188015, 2023). "Our study shows that TNBC patients have significant expression of claudin-1, and that this expression correlates with invasive phenotype, sentinel lymph node positivity, higher tumour grade, higher clinical and TNM stage, and adverse survival outcome." (PMID 37102018, 2023). "Accordingly, AMPK activation overrides claudin-1-induced tumor invasion, suggesting a role of a claudin-1/AMPK/TGF-β axis in these tumors." (PMID 37686483, 2023). "This strategy takes advantage of the tumor cell changes (e.g. induction of CLDN1 expression by oxaliplatin treatment) that occur during drug resistance development." (PMID 37041570, 2023). "In fact, through multivariate analysis, one study identified reduced claudin-1 expression as an independent predictor of tumor recurrence." (PMID 38188015, 2023). "Subsequently, protein levels of CycA, EDN1, CLDN1, and pro-apoptotic proteins (Caspase-3 and Bax) in tumor tissues were detected by western blot." (PMID 38105218, 2023). "Claudin 1 was inclined to be highly expressed in the membrane and cytoplasm of tumour cells in the periphery of tumour nest." (PMID 36714681, 2023). "From day 3 after oxaliplatin treatment (2 mg/kg), CLDN1 membrane expression increased progressively and more strongly in treated than untreated mice, independently of the tumor growth." (PMID 37041570, 2023). "In our study, claudin-1 expression is correlated with invasion, sentinel lymph node metastases, higher tumour grade, higher clinical and TNM stage, and adverse clinical outcome in TNBC patients." (PMID 37102018, 2023). "The overexpression of CLDN7 promotes proliferation, migration, invasive potential, and tumourigenesis of CRC, while decreased CLDN1 expression was proved to stimulate tumour cell invasion and metastases of PC." (PMID 38201579, 2023). "We found that CLDN1 expression was significantly correlated with the two conventional criteria of histological assessment: Blazer score (p = 0.029) and tumor regression grading (TRG) (p = 0.017)." (PMID 37041570, 2023). "A tumour-suppressive function of CLDN1, 4, and 11 has been indicated for GC, while this function of CLDN4 has been indicated in the pathogenesis of PC." (PMID 38201579, 2023). "Tumor-bearing mice exhibited several markers of colonic barrier disruption, including dampened expression of tight junction proteins (Cldn1 and Ocln) and elevated circulating lipopolysaccharide binding protein (LBP)." (PMID 35248004, 2022). "We found that the expression level of Claudin-1 was upregulated in tumor tissue compared to adjacent normal tissues." (PMID 35818041, 2022). "Numerous CLDN1-targeting antibodies, including 3A2 and 6F6, have been demonstrated to be tumor suppressive." (PMID 36620607, 2022). "In esophageal squamous carcinoma, CLDN1 was revealed to promote tumor development and invasion via autophagy activation through the 5′AMP-activated protein kinase/STAT1/Unc-51 like autophagy activating kinase (ULK1) signaling pathway." (PMID 36193204, 2022). "Tumor-bearing mice had lower expression of tight junction proteins Claudin-1 (Cldn1) and Occludin (Ocln) in the colon, while Resected mice only had lower expression of Ocln (but tended to have lower Cldn1) relative to Control mice." (PMID 35248004, 2022). "While high-fat feeding resulted in accelerated tumor formation rates, this was prevented by depletion of either CLDN1 or LCN2." (PMID 35013251, 2022). "In mouse models, claudin-1 overexpression obviously increases the activity of Wnt and Notch signaling, leading to the proliferation of tumor cells." (PMID 34354941, 2021).